XNDC1N (XRCC1 N-terminal domain containing 1, N-terminal like)
Tractability: No criterion of Open Targets' tractability assessment is met for any kind of drug.
Gene: Protein-coding gene on chromosome 11 (71,865,504 to 71,928,654, reverse strand). Ensembl gene ENSG00000254469.
Subcellular location (Human Protein Atlas): Nucleoli; Mitotic chromosome
Gene Ontology:
Molecular function: damaged DNA binding
Biological process: single strand break repair
Cellular component: nucleolus; nucleus
Genetic constraint (gnomAD): Loss-of-function variants: 0 observed, 0.31 expected, observed/expected ratio (o/e) 0, 90% interval 0 to 1.86. That is too few expected variants to judge how well the gene tolerates losing a copy. Missense variants: 55 observed, 62.92 expected, observed/expected ratio (o/e) 0.87, 90% interval 0.7 to 1.09. Synonymous variants: 24 observed, 19.12 expected, observed/expected ratio (o/e) 1.26, 90% interval 0.91 to 1.74.
Homologues: Orthologues: macaque XNDC1 (76% identical), dog XNDC1 (71% identical), mouse Xndc1 (70% identical), chimpanzee XNDC1N (67% identical), tropical clawed frog xndc1n (44% identical), zebrafish xndc1 (44% identical), Drosophila melanogaster XRCC1 (21% identical). Paralogues in human: XRCC1 (29% identical).